IL1B (interleukin 1 beta)
Diseases named in the same sentence as IL1B in open-access papers (continued):
Sharing a sentence is not in itself a finding about the gene and the disease.
breast cancer (continued). "A study that combines patient samples, humanized mouse models, and genetic manipulation of breast cancer cells demonstrated that β tumor-derived IL-1β significantly contributes to the metastatic process." (PMID 39125732, 2024). "Further, IL-1β has been shown to promote tumor invasiveness in breast cancer by activating the IL-1β/IL-1RI/β-catenin signaling pathway, leading to β-catenin accumulation and nuclear translocation." (PMID 39769450, 2024). "Specifically, Interleukins (ILs) such as IL-6, IL-8, IL-1β, and IL-11 have been identified as important regulators in the onset and advancement of breast cancer spreading to the bones." (PMID 39125732, 2024). "In a preclinical study, IL1B produced by tumor cells drives the metastasis and growth of breast cancer in the bone microenvironment." (PMID 39125732, 2024). "IL-1β derived from the bone marrow significantly enhances the colonization of breast cancer cells in the bone." (PMID 39125732, 2024). "Our results agree with a previous study indicating inhibition of inflammasome activation and IL-1β signaling can decrease breast cancer growth and metastasis." (PMID 38254674, 2024). "In breast cancer, IL1β has a complex role in bone metastasis, suppressing growth in primary tumors while promoting the growth of osteolytic metastases." (PMID 39766172, 2024). "Innate immune cytokines such as IL-1β and IL-18 have been shown to promote breast cancer progression in animal models." (PMID 39769450, 2024). "In another study, Anakinra, or the IL1β antibody, Canakinumab, reduces metastases and nearly eradicates breast cancer growth in the bone." (PMID 39125732, 2024). "Research illustrates that the Wnt pathway plays a major role in the formation of bone metastasis in breast cancer by interacting with IL-1β and dictating the stemness of breast cancer cells." (PMID 38243240, 2024). "In a later study, the authors showed that breast cancer cells engineered to overexpress IL-1β (MDA-MB-231- IL1B+) had enhanced bone-homing capabilities." (PMID 38334625, 2024). "IL1β: In a recent study, using single-cell RNA sequencing data from various breast cancer subtypes (ER+/PR+, HER2+, and TNBC), the study identified that IL1β is significantly upregulated in triple-negative breast cancer (TNBC) samples." (PMID 39125732, 2024). "Breast cancer cell lines genetically modified to overexpress IL-1β presented increased EMT and metastasis." (PMID 39044824, 2024). "IL-1β appears to have opposing functions in breast cancer, as high levels in the tumour micro-environment inhibit tumour growth while on the other hand it seems to enhance metastasis in bone." (PMID 38468349, 2024). "The overexpression of NLRP1 and increased levels of IL-1β in the tumor microenvironment have been emphasized to promote breast cancer malignity, progression, and migration." (PMID 38990306, 2024). "Based on the study, membrane derived soluble CD44 secreted by breast cancer cells triggered IL1-β expression in TAMs promoting cancer cell EMT and metastasis." (PMID 39044824, 2024). "Here the authors report that ETS1-driven caspase-1 expression is a feature of TNBC and is required for IL1β-mediated macrophage recruitment and breast cancer growth." (PMID 39353903, 2024). "Gene expression analysis suggested the potential of NLRP3 inflammasome modulation to counterbalance breast cancer cells growth by activating the immunogenic cell death (pyroptosis) and inhibiting the activity of pro-inflammatory cytokines, IL-1β and IL-18." (PMID 39433537, 2024). "Interleukin-1B (IL-1B) is a potent pro-inflammatory cytokine that plays multiple, pivotal roles, in the complex interplay between breast cancer cells and the bone microenvironment." (PMID 38800348, 2024). "Among these cytokines, interleukin 1-β (IL-1β) is known as a master regulator of inflammation and has been shown to promote angiogenesis, invasion, and mobility in breast cancer 28–31." (PMID 39801513, 2024).
breast cancer (continued). "IL-1B also influences the tumor microenvironment by enhancing desmoplasia and immune suppression in pancreas and breast cancer." (PMID 38346068, 2024). "To further explore the association between TIB, IL-1β and breast cancer invasiveness, we examined the relationship between TIB density, IL-1β expression, and invasion in tumor microarrays containing tissue from 90 hormone receptor negative DCIS." (PMID 39801513, 2024). "It has been reported that primary breast cancer patients with increased IL-1β expression are more likely to develop bone metastasis." (PMID 38762529, 2024). "Clinical trials have identified increased serum IL-1β levels and intratumoral IL-1β expression in breast cancer patients, positively correlated to tumor stage and progression." (PMID 38254674, 2024). "A cohort study done in in early-stage breast cancer patients investigated the changes in cytokine (IL-1β, TNF-α and IL-4) levels before and after chemotherapy demonstrated higher IL-4 levels in patients after receiving the chemotherapy treatment." (PMID 39355088, 2024). "In line with this, melanoma also exhibited the largest concentration of IL-1β, TNFα, and Sirtuin-1, which was followed by the concentration determined in mammary carcinoma homogenates." (PMID 38698774, 2024). "In renal and breast carcinoma, several studies have shown that IL-1β drives a tumor-promoting transcriptional profile." (PMID 39224600, 2024). "Several other studies in breast cancer examining IL-1β inhibition either alone or in combination with chemotherapy or immunotherapy in the metastatic setting are ongoing (NCT04121442, NCT03742349, NCT02900664)." (PMID 37065483, 2023). "Astrocytes were demonstrated to support lung and breast cancer cells metastasis by producing interleukin-1 beta (IL1β) and tumor necrosis factor-alpha (TNFα)." (PMID 36835266, 2023). "IL-1β was also reported to significantly influence the overall survival and distant metastasis of breast cancer." (PMID 38031068, 2023). "First, we observed that MCC950 reversed breast cancer-induced increased expression of NLRP3 inflammasome-associated genes in astrocytes, probably through inhibition of IL-1β and a subsequent feedback effect on priming." (PMID 37749707, 2023). "IL-1β can activate the β-catenin signaling pathway to induce epithelial–mesenchymal transition (EMT) in breast cancer cells." (PMID 37138170, 2023). "A systematic review by Tyagi et al14 presented that IL‐6, IL‐1β, and TNF‐α were associated with cognitive dysfunction in post‐chemotherapy breast cancer patients." (PMID 36965094, 2023). "Docosahexaenoic acid triggers caspase-1 activation, GSDMD maturation, and IL-1β secretion in breast cancer cell line, MDA-MB-231, through lysosomal damage and ROS formation." (PMID 36932407, 2023). "Anakinra, an IL-1Ra, has been shown to suppress breast cancer growth by reducing the secretion of IL-1β and IL-22." (PMID 38066523, 2023). "More importantly, both MCC950 and neutralization of IL-1β prevented astrocyte-conditioned media-induced augmentation of breast cancer cell proliferation in vitro, both in the human and mouse models." (PMID 37749707, 2023). "After the activation of PI3K/AKT in the breast cancer cells, the expression of IL-6, IL-1β, and tumor necrosis factor-α (TNF-α) in breast cancer cells is increased." (PMID 36624542, 2023). "We mainly detected high expression of TGF-β, IL-1β, and IL-10 in basal-like breast cancer compared to healthy and luminal biopsies." (PMID 37340387, 2023). "For example, in one report NLRP3 inflammasome activation was shown to promote autocrine IL-1β secretion in breast cancer, in turn inducing the epithelial-mesenchymal transition and metastatic progression." (PMID 37885032, 2023). "To prove that astrocyte-conditioned media increased the proliferation of breast cancer cells through inflammasome activation and IL-1β secretion, we treated astrocytes with MCC950, a specific NLRP3 inhibitor." (PMID 37749707, 2023).
breast cancer (continued). "He finished by showing data that highlighted the pro- and anti-tumour effects of IL-1β on different inflammatory populations within primary breast cancer tumours." (PMID 37846765, 2023). "Another downstream event of IL-1β in breast cancer is NF-κB that enhanced cell invasion and activation." (PMID 36932407, 2023). "As additional proof of inflammasome priming in astrocytes, human brain samples with breast cancer metastases were immunostained for IL-1β, which was also found to colocalize with GFAP and NLRP3 in the peritumoral regions." (PMID 37749707, 2023). "It was reported that an increased level of IL-1β in serum was identified in breast cancer patients and related to an advanced stage and poor prognosis." (PMID 36823153, 2023). "Recent studies focusing on breast cancer and renal cell carcinoma have shown that neutralizing IL‐1β can rescue the immunosuppressive microenvironment and work synergistically to block PD‐1, but the detailed mechanisms need to be further explored." (PMID 37009412, 2023). "Without distinguishing between fibroblasts and macrophages, we found that NLRP3, caspase-1, ASC, IL-1β, and IL-18 were all elevated in the breast cancer immune-stromal cells." (PMID 38031068, 2023). "In the study of prognostic‐related gene expression, breast cancers showed considerably lower levels of the pyroptosis pathway effector proteins caspase 1, IL‐1β, and GSDMD compared with nearby normal tissue." (PMID 37752941, 2023). "IL1β knock-out mice treated with orthotopically introduced breast cancer cells showed initial tumor growth followed by subsequent regression, due to the recruitment of alternative inflammatory monocytes in the tumor microenvironment." (PMID 37065483, 2023). "TAM-derived IL-1β can increase cyclo-oxygenase-2 (COX-2) expression in breast cancer cells and contribute to cancer progression, migration/invasion, regulate metastatic process, and EMT." (PMID 36835413, 2023). "Meanwhile, increasing evidence had revealed that IL-1β promotes the proliferation and metastasis of breast cancer cells in vitro and in vivo." (PMID 36823153, 2023). "Recent studies have also shown that NAT1 promotes bone metastasis in luminal-type breast cancer by regulating the bone microenvironment through the NF-κB/IL-1B signaling pathway." (PMID 38041134, 2023). "In breast cancer, other cytokines such as IL‐6, IL‐1α, IL‐1β, IL‐8, TNF‐α/β, TGF‐β, and GM‐CSF are also known to stimulate angiogenesis." (PMID 36815234, 2023). "The session began with a talk from Dr Jiabou Zhou, a recent PhD graduate from the University of Sheffield, delivering a presentation on the role of interleukin 1 beta (IL-1β) in breast cancer bone metastases." (PMID 37846765, 2023). "To recapitulate the systemic increase of IL-1β and IL-23 in mammary tumor-bearing mice, we stimulated CD3+ T cells isolated from lungs of WT mice in vitro with these cytokines and examined tumor-associated protein expression in CD27− γδ T cells." (PMID 36480166, 2023). "Another study highlighted that NLRP3-induced pyroptosis and IL-1β secretion create an immune suppressive environment in breast cancer." (PMID 37629059, 2023). "Previously, brain metastatic breast cancer cells were shown to secrete IL-1β in vitro, which activated Notch and transforming growth factor-β2 (TGF-β2) signaling in astrocytes." (PMID 37749707, 2023). "On the one hand, IL-1β-deficient was associated with the decreased infiltration of MDSCs and increased CD8+ cytotoxic T cells, thus activating tumor immunity in breast cancer." (PMID 36823153, 2023). "Previously, we showed in vitro that IL-1β treatment of non-invasive human breast cancer MCF-7 cells promoted their transition to a malignant phenotype (6D cells)." (PMID 37686042, 2023). "In terms of fibronectin production, the breast cancer cells used in our study were more responsive to IL-1β than to TNF-α or IL-6." (PMID 36922898, 2023).
breast cancer (continued). "Highly increased serum levels of the inflammatory cytokine IL-1β have been related to the tumor stage in breast cancer patients as an important prognostic marker." (PMID 37686042, 2023). "In the present study, we observed that IL-1β levels were reduced in patients with lymph node metastasis, reinforcing the immune dysfunction reported in breast cancer patients exposed to pesticides reported by others." (PMID 37942322, 2023). "In vitro studies have recently shown that primary breast cancer cells cocultured with monocytes exhibit increased IL-1β, IL-8, and MMPs, suggesting that inflammation and subsequent recruitment of immune cells promote breast cancer development at early stages." (PMID 36835413, 2023). "The NLRP3 inflammasome has been shown to promote breast cancer growth and metastasis by inducing IL-1β secretion, which stimulates angiogenesis, immune evasion, epithelial-mesenchymal transition (EMT), and stemness." (PMID 37715239, 2023). "Our results found that breast cancer survivors with psychological distress showed significantly higher levels of IL‐1β, TNF‐α, and IL‐4." (PMID 36965094, 2023). "MDSC were isolated from the blood of mice injected with mammary carcinoma cells or with IL-1β-transfected mammary carcinoma cells as an inflammatory stimulus." (PMID 37762077, 2023). "Interleukin-1β (IL-1β), vascular endothelial growth factor (VEGF), and IL-4 serum levels and new genetic mutations in breast cancer (BC) patients were assessed in the current study." (PMID 36619680, 2023). "In another study, higher levels of depressive symptoms were associated with higher levels of IL-1β, and TNF-α post-surgery in breast cancer patients with a mean age of 50 years." (PMID 35547250, 2022). "While IL-1β is an inflammatory protein, IL-5 and eotaxin are both involved in allergic inflammation and asthma, but they are involved in breast cancer progression as well." (PMID 36158648, 2022). "In this review, we focus on what is known about the role of IL-1α and IL-1β in breast cancer (BCa) progression and therapeutic resistance, and state evidence for the role of NF-κB in mediating IL-1-induced BCa progression and therapeutic resistance." (PMID 35626710, 2022). "IL1β, a pivotal regulator of the systemic inflammatory response, is produced by macrophages in breast cancer." (PMID 35464064, 2022). "Another study also demonstrated that NLRP3 pyroptosis caused IL-1β maturation and the resulting CCL5, CXCL12, CCL2, and CXCL5 expression, which enhanced metastasis of breast cancer by recruiting MDSC and M2 macrophages." (PMID 36119049, 2022). "This study also provided evidence that IFN-γ had a similar effect to IL-1β on increasing PIGR expression in breast cancer cells." (PMID 36207349, 2022). "Previous studies have demonstrated that inhibiting IL1β significantly reduced breast cancer bone metastasis, but the administration of biological agents such as Canakinumab has severe adverse effects on the immune system of cancer patients." (PMID 36230739, 2022). "Taken together, these studies reveal a detrimental role of IL-1β in breast cancer progression and a prominent role of myeloid cell-derived IL-1β production." (PMID 35631400, 2022). "Most existing studies on the effects of exercise on inflammatory factors and IGF systems in breast cancer survivors examine IL-6, IL-10, IL-1β, TNF-α, CRP, IGF-1, and IGFBP-3 levels." (PMID 36482346, 2022). "The upregulation of both TNF-α and IL-1β was observed in breast cancer patients with reoccurring disease." (PMID 35565306, 2022). "Most malignancies, including breast cancer, have elevated levels of IL-1β which is bounteous in the TME, in which it can avail tumor proliferation, but also antitumor activities." (PMID 36119049, 2022). "Evidence suggests that inhibiting IL-1 signalling with the IL1R antagonist, Anakinra, or the IL1β antibody, Canakinumab, prevents metastasis and almost eliminates breast cancer growth in the bone." (PMID 36230739, 2022).
breast cancer (continued). "The function of IL-1 signalling on viability and migration and invasion of breast cancer cells was assessed, in vitro, upon IL1B or IL1R1 overexpressing or treatment with anti-IL-1 signalling." (PMID 36230739, 2022). "Previous studies reported that increased IL-1β level was reported to be related with bone metastasis in breast cancer and promoted immune suppression in pancreatic cancer patients." (PMID 35626430, 2022). "IL-1 receptor blockade assay using IL-1 receptor antagonist (IL-1RA) was performed to confirm the action of IL-1β secreted from M1 macrophages on the expression of PIGR in breast cancer cells." (PMID 36207349, 2022). "In breast cancer, IL-1β has also been shown to up-regulate matrix metalloproteinase (MMP) 2, and MMP9, thereby promoting invasiveness and vasculogenic mimicry of tumour cells." (PMID 36353102, 2022). "This regulatory role of IL-1β is in accordance with experiments in a NETs-dependent breast cancer model, in which the inhibition of IL-1β leads to the attenuation of thrombosis." (PMID 35884400, 2022). "It has been reported in a review that NLRP3, IL-1β, and IL-18 motivate the development of tumors in lung cancer, melanoma, and breast cancer." (PMID 36119049, 2022). "IL-1β is able to induce the progression of breast cancer from a benign to a malignant stage, resulting in the deregulation of several growth factors, cytokines, and chemokines." (PMID 36499741, 2022). "Furthermore, IL1B could be predicted the risk of breast cancer patients developing bone metastases." (PMID 36253777, 2022). "We and others found that acute IL-1α or IL-1β exposure represses ERα and PR mRNA and protein accumulation in breast cancer cell lines." (PMID 35626710, 2022). "In the TME, IL-1β has protumoral properties in promoting angiogenesis and cancer metastasis in a range of cancer types, including breast cancer, liver cancer, colon cancer, and melanoma." (PMID 36264639, 2022). "Our previous study showed that tumour-derived IL1β was much more potent at promoting the migration of MDA-MB-231 and MCF7 breast cancer cells compared with IL1β from the microenvironment." (PMID 36230739, 2022). "In advanced stage breast cancer, the proinflammatory cytokine IL-1β is overexpressed due to large proportions of activated myeloid cells in the tumor microenvironment (TME)." (PMID 35631400, 2022). "In a murine model of breast cancer, an anti-PD-1 and anti-IL-1β treatment revealed synergistic effects for enhancing anti-tumor immunity." (PMID 36293159, 2022). "While the trial did not have enough power to look at different cancer subtypes, breast cancer tumor cells have been shown to produce IL-1B, which promotes epithelial-to-mesenchymal transition, migration, and invasion of breast cancer cells." (PMID 35669467, 2022). "As the upstream regulatory cytokine of G-CSF, interleukin-1 beta (IL-1β) was found to influence NET production in breast cancer." (PMID 36384979, 2022). "The action of the inhibitors of enzymes that regulate DNA methylation (DNMTs and TETs) on the IL-1β-induced EMT process of MCF-7 breast cancer cell line was subsequently assessed." (PMID 36499741, 2022). "Global removal of IL1β in IL1β knockout mice leads to increased growth of primary mammary tumours, and administration of Anakinra/Canakinumab also increases the growth of primary breast cancers in mice." (PMID 36230739, 2022). "It has been shown that breast cancer cell-derived sEVs enhance TAM expression of IL-1β, IL-6, and TNF-αand that TANs inhibit 4T1-cell sEV secretion, resulting in a marked decrease in IL-1β, IL-6, and TNF-α." (PMID 36096820, 2022). "Consistently, a recent report using a 4T1 murine model of breast cancer showed addition of anti-PD-1 to anti-IL-1β, resulting in complete tumor abrogation through alterations of immunosuppressive cells." (PMID 35631400, 2022).